RB1 (RB transcriptional corepressor 1)
Diseases named in the same sentence as RB1 in open-access papers (continued):
Sharing a sentence is not in itself a finding about the gene and the disease.
tumor (continued). "Given that Rb1 was described as a prototypical tumor suppressor more than 40 years ago, there is a huge amount of evidence regarding its post-translational modifications." (PMID 35267571, 2022). "RB, a rapidly growing tumor derived from embryonal retinal cells, is usually caused by biallelic loss of the RB1 gene, a tumor suppressor gene at chromosome 13q14, during infancy and childhood." (PMID 35982972, 2022). "In this study, we observed that miR‐192‐5p affects tumour EMT by regulating RB1, inducing the secretion of IL‐10 to promote FOXP3+Treg cell differentiation and PD‐1 expression on Tregs in the TME." (PMID 35969010, 2022). "RB1 is a tumor suppressor that is inactivated by phosphorylation by a complex of CDK4 and CDK6 with cyclin D." (PMID 36003783, 2022). "In this study, there were insufficient RB1+/+ tumor samples for gene expression or protein analysis." (PMID 35982972, 2022). "It was the first modification identified to be crucially important for Rb1 function as a tumor suppressor." (PMID 35267571, 2022). "The IHC staining revealed higher expression of RB1 in tumor tissues as compared to that in normal tissues (P = 0.019)." (PMID 35299734, 2022). "The RB retinoblastoma-associated protein (pRB, RB1) represents the first identified tumor suppressor." (PMID 35361964, 2022). "RB1 is a well-known tumor suppressor gene, and its deletion can enhance glycolytic metabolism and driving tumor progression." (PMID 34980012, 2022). "The RB1 mutations were identified at 5, 8, and 13 months after initiation of CDK4/6i in each patient from circulating tumor DNA (ctDNA) analyzed by commercially available NGS-based assay." (PMID 35804935, 2022). "To investigate the effects of miR‐192‐5p/RB1 on tumourigenesis and immunosuppression in vivo, we performed a subcutaneous tumour xenograft experiment using BGC‐823 cells." (PMID 35969010, 2022). "It is important to note that in RB1m1/m2 hRBOs, we found that the tumor primary foci appeared as early as DD42 during hROs development, which is earlier than the neoplasm formation at DD60 to DD75 in hROs derived from RB1-depleted hESCs." (PMID 36714839, 2022). "This is, to our knowledge, the first study showed that the small-molecule compound GSK503 efficiently restored pRB expression and suppressed tumorigenesis in non-RB1-mutational tumor cells." (PMID 36175480, 2022). "RB1, as a tumor suppressor, canonically regulates cell cycle progression and represents a downstream target for CDK4/6 or CDK2 inhibitors that are in clinical use." (PMID 36082941, 2022). "Alteration in the gene locus coding for Rb1 protein is considered the first evidence showing the crucial role of tumor suppressor genes in cancer development." (PMID 35267571, 2022).
tumor (continued). "We conclude that RBL1 and RBL2 do have important tumor suppressor activity in some contexts, but RB1 remains the dominant tumor suppressor in the family." (PMID 35368709, 2022). "When phosphorylated by CDK3/cyclin-C, RB1 is a major regulator of cell division and works as a tumor suppressor, promoting the G0-G1 transition." (PMID 36531719, 2022). "Evidence for RB1 mediated tumor suppression is more readily detected across a wider spectrum of tissues and biological contexts while evidence for RBL1 and RBL2 tumor suppressor activity is more restricted." (PMID 35368709, 2022). "The tumour suppressor RB1 is a key regulator of the G1/S transition of the cell cycle and is required for the stabilisation of heterochromatin." (PMID 35326573, 2022). "The different patterns of RB1 in adjacent non-tumor ovarian tissues and OC samples were also analyzed." (PMID 35299734, 2022). "Together these data suggest that tumor development from proliferating cone precursors to premalignant retinoma and development of malignant Rb tumors is replicated within the hESC RB1-null organoids." (PMID 35325233, 2022). "We propose that this pRb-specific function is a good candidate mechanism accounting for RB1’s dominant role in tumor suppression." (PMID 35368709, 2022). "TCGA-confirmed tumor suppressor genes with a lower copy number in the two cells included RB1 and CDKN2A/B." (PMID 36430324, 2022). "Sequencing data from the sensitive tumor (2R) revealed a CDKN2A homozygous loss and concomitant RB1 heterozygous loss." (PMID 36071033, 2022). "In summary, our findings established that the miR‐192‐5p‐RB1‐NF‐κBp65 signaling pathway promotes tumour EMT, metastasis and Treg cell differentiation in GC." (PMID 35969010, 2022). "For example, two regulatory PP1 subunits, MYPT and SPN, play a role in a tumor suppressor that is mediated by stimulating Rb1 dephosphorylation." (PMID 35267571, 2022). "We found a stronger signal of the level of H3K27me3 at the RB1 promoter in tumor cells (first panel, lane 3)." (PMID 36175480, 2022). "Repression by promoter methylation of p16INK4a, a cyclin-dependent kinase (CDK) inhibitor that enforces RB1 tumor-suppressive activity by inhibiting its phosphorylation by CDK4 and CDK6, is common in PanNETs." (PMID 36428573, 2022).
tumor (continued). "The use of TALENs in this study to generate the targeted somatic inactivation of the rb1 tumour suppressor in G0 mosaic animals helped in understanding their role in driving tumorigenesis, without causing embryonic lethality." (PMID 36077320, 2022). "RB1 gene codes for retinoblastoma protein which exerts its anti-tumor effects by sequestering the activity of E2F transcription factors." (PMID 35359459, 2022). "This is consistent with the cell of origin being similar for RB1-deficient and RB1-proficient, MYCN-induced neoplasms." (PMID 35729105, 2022). "From the list of targetable miRNAs, miR-132 is particularly interesting as studies have shown that its function in pancreatic cancer is to target the tumor suppressor Rb1 mRNA, which promotes cancer tumor growth when inactivated." (PMID 36013894, 2022). "Among the predicted genes, the predicted gene RB1, as a tumour suppressor that regulates the cell cycle, is known to participate in immune cell infiltration and multiple signaling pathways, such as the NF‐κB signaling pathway." (PMID 35969010, 2022). "Feeding the CDK4/6 inhibitor ribociclib to mice bearing human LPS xenografts ultimately decreased tumor biomarkers, including Rb1 phosphorylation." (PMID 35884441, 2022). "Three studies focused on in vitro differentiation of RB1 mutant human pluripotent stem cells into retinal organoids for 90 to 150 days, whereas one study investigated tumor formation of organoid-derived cells of d45 in orthotopic xenograft models." (PMID 35565295, 2022). "The TALEN-mediated somatic inactivation of zebrafish retinoblastoma 1 (rb1) tumour suppressor predominantly induces CNS-PNET tumours at a high frequency." (PMID 36077320, 2022). "Collectively, our studies indicate that miR‐192‐5p/RB1 promotes EMT of tumour cells, and the miR‐192‐5p/RB1/NF‐κBp65 signaling axis induces Treg cell differentiation by regulating IL‐10 secretion in GC." (PMID 35969010, 2022). "RB1 is a tumor suppressor gene detected in retinoblastoma, and RB protein binds to the transcription factor E2F and inhibits its transcriptional activity, thereby suppressing cell growth." (PMID 34440096, 2021).
tumor (continued). "A more aggressive clinical course is reported in large segment 13q deletion attached with retinoblastoma 1 (RB1) gene, which is considered as tumor suppressor gene." (PMID 34522485, 2021). "The frequency that RB1 gene loci undergo homozygous deletion in cancer is the fourth highest among tumor suppressor genes following INK4A, PTEN and SMAD4." (PMID 34359636, 2021). "We reverted the germline RB1 mutation in two of the lines (SJRB-iPSC-4-REV and SJRB-iPSC-6-REV) using CRISPR-Cas9 and performed the same tumor formation experiments in parallel with those lines." (PMID 34315877, 2021). "If this is the case for many other pRB‐mediated chromatin regulation events, it would be important to determine how the deregulated E2F activity in tumors with RB1 loss would impact the tumor epigenomes." (PMID 32840881, 2021). "In the tumor cell line with acquired resistance to palbociclib, it was demonstrated that resistance to CDK4/6 inhibitors was mediated through Rb1 loss, and restoration of Rb1 expression rendered tumor cells sensitivity to the CDK4/6 inhibitor." (PMID 34123801, 2021). "KRAS amplification and homozygous deletion in PTEN and RB1 were detected in tumor samples collected from the patient." (PMID 33670958, 2021). "Increased expression of p16 (encoded by CDKN2A gene) occurs following E7-mediated phospho-RB1 inactivation, allowing p16-expressing tumor cells to bypass cell cycle arrest." (PMID 35126105, 2021). "A subsequent mitotic error results in the loss of one copy of chromosome 18 in multiple EC cells, which would decrease MIR1 expression, increase CDK4 expression, and attenuate the RB1 tumor suppressor pathway." (PMID 34680217, 2021). "Hyperactivation of Ras-MEK-ERK signaling is another way tumor cells acquire resistance to CDK4/6 inhibitor therapy as the pathway converges on RB1." (PMID 33456709, 2021). "Comprehensive molecular analysis, including DNA array-based methylation profiling and sequencing-based methodologies, were critical for classification and understanding the complex mechanism of RB1 inactivation in this diagnostically challenging tumor." (PMID 33827698, 2021). "This strongly suggests that RB1 deletion is an important molecular driver event in the development of these neoplasms, as it is conserved throughout this tumor family." (PMID 33802620, 2021). "The wide spectrum of rearrangement patterns capable of disrupting RB1 highlight the need for exhaustive searching for genomic aberrations in Rb tumours." (PMID 33670346, 2021).
tumor (continued). "Five tumours demonstrated complex interchromosomal rearrangement patterns transecting RB1 through a variety of structural variations including translocations to other chromosomes (PD37492, PD37493, PD37494, PD37495, and PD37497)." (PMID 33670346, 2021). "The first product discovered, p16INK4a (Inhibitor of CDK4/6), is a cyclin dependent kinase (CDK) inhibitor that enforces RB1 tumor suppressive activity by specifically inhibiting CDK4 and CDK6." (PMID 34680266, 2021). "As alluded to the introduction, mostly in an E2F-dependent manner, RB1 status affects the milieu surrounding tumor cells including chemokine/cytokine secretion, extracellular matrix, immune cells or remote organs to be metastasized." (PMID 34359636, 2021). "We recapitulated these functional interactions among p16INK4a/RB1, Pten, and Ras oncogenic pathways, resulting in a highly aggressive tumor phenotype in our model that will be useful for high-throughput screens, for example done in parallel with mouse studies." (PMID 33591981, 2021). "This effort discovered succinyl lyase A2 (SUCLA2) gene that locates around 302 kb away from RB1 tumor suppressor gene in human chromosome 13q14.2." (PMID 34359636, 2021). "Among three tumours expressed Rb1 and p16, one Rb1 positive tumour with diffuse labelling for p16 was found to have a CDKN2A mutation by NGS." (PMID 33737597, 2021). "From this, we found that much like our RPE1 cells, TCA cycle components were lower in RB1−/− mutant tumor samples, whilst the proteins necessary for enhanced purine and pyrimidine biosynthesis were elevated." (PMID 34404904, 2021). "Clinical screening using MLPA detected a suspected amplification of exons 12 to 17 of RB1 in the tumour and possible low-level amplification in the normal blood sample." (PMID 33670346, 2021). "In a majority of human cancers, RB1 function is suppressed during tumor progression through various mechanisms." (PMID 34359636, 2021). "A large somatic deletion of RB1 involving exons 8 to 11 was identified in the tumour of the right eye." (PMID 33670346, 2021). "Mounting evidence implicates the role of the INK4A/ARF (originally called CDKN2A) gene locus and retinoblastoma 1 (RB1) tumor suppressor pathway in pNET pathogenesis." (PMID 34680266, 2021). "In this way, we found that a number of well-known oncogenes, including MYC and SOX9, were annotated as targets of tumor-specific SEs, while several tumor suppressor genes in LUAD, such as DLC1 and RB1, were linked to normal-specific SEs." (PMID 34001209, 2021).